ATF3 (activating transcription factor 3)
Diseases named in the same sentence as ATF3 in open-access papers (continued):
Sharing a sentence is not in itself a finding about the gene and the disease.
asthma (9 papers, 2015 to 2025). "miR‐27a is associated with the pathogenesis of asthma, and ATF3 can attenuate the inflammatory response associated with allergic airway disease." (PMID 37385291, 2025). "Serum miR‐27a‐3p was highly expressed, whereas ATF3 was poorly expressed in BA children, and they were significantly correlated with airway inflammation, had good diagnostic values in BA children, and were independent risk factors for asthma." (PMID 37385291, 2025). "In addition, according to a previous study, ATF3 has a significant correlation with asthma and is associated with the risk of asthma." (PMID 37385291, 2025). "Moreover, ATF3 has been discovered to be associated with the risk of asthma." (PMID 37385291, 2025). "Studies have reported that ATF3 has a significant correlation with asthma and can attenuate the inflammatory response in allergic airway disease." (PMID 37385291, 2025). "Indirectly perturbed genes near ATF3 and EGR2 in the network include C2, SERPING1, ZG16B, and CEACAM3, all of which have been linked to immune response, asthma, or auto-immune diseases." (PMID 33095769, 2020). "Furthermore, multiple genes, such as ATF3, activation‐induced cytidine deaminase (AICDA), thymic stromal lymphopoietin (TSLP), and endothelin receptor type A (EDNRA), are associated with asthma." (PMID 37385291, 2025). "Subsequently, ATF3 regulatory TL1A/DR3 signaling was enriched in OVA-induced asthma." (PMID 35359966, 2022). "Our findings illustrated that in the serum of children with BA, miR‐27a‐3p targets ATF3 and inhibits ATF3 levels, promotes airway inflammation, and upregulates the levels of IL‐17, IL‐6, TNF‐a, and EOS, thereby promoting the occurrence of asthma." (PMID 37385291, 2025). "We identified SLC7A11, SLC2A12, ZEB1, ATF3, and HIC1 common between DEGs and TFs involved with asthma and ferroptosis." (PMID 34257337, 2021). "They include RBM42, STX5, and TRIM41 in asthma, CYP27A1, GM2A, LGALS9, SPI1, and NLRC4 in COPD, as well as ATF3, PPP1R15A, ZFP36, SOCS3, NAMPT, and GADD45B in IPF." (PMID 31952466, 2020). "In addition, ATF3 directly binds to CRE sites in the IL-4, IL-5 and IL-13 promoter regions and ATF3 binding sites were found enriched in a recent epigenomic analysis of regulated genes that play a role for TH2 memory cell differentiation and asthma susceptibility." (PMID 26459392, 2015). "PerturbNet provided new insights into the molecular characterization based on ATF3-centered pathway for the known GWAS SNP whose functional role in asthma has not been fully elucidated." (PMID 33095769, 2020). "These genes included RBM42, STX5, and TRIM41 in asthma, CYP27A1, GM2A, LGALS9, SPI1, and NLRC4 in COPD, ATF3, PPP1R15A, ZFP36, SOCS3, NAMPT, and GADD45B in IPF, LRRC48 and CETN2 in asthma-COPD, COL15A1, GIMAP6, and JAM2 in asthma-IPF and LMO7, TSPAN13, LAMA3, and ANXA3 in COPD-IPF." (PMID 31952466, 2020).
breast tumors (9 papers, 2008 to 2025). "The hypoxic niches generated within the breast tumors positively stained for ATF3 and coincided with the staining of a universal hypoxia marker CAIX, showing a positive correlation." (PMID 40016181, 2025). "Together, our results suggest that the BK5.ATF3 transgenic model strongly reflects human basal-like breast tumors." (PMID 33652981, 2021). "The Atf3 gene is located on human chromosome at 1q32.3 within the 1q amplicon, which is the most frequently amplified region in human breast tumor: ~53%." (PMID 30373101, 2018). "Several markers commonly used to classify human breast tumors were analyzed in these tumor specimens to begin to understand the genesis of the ATF3-induced tumors." (PMID 18808719, 2008). "Immunohistochemical studies indicated that a subset of human breast tumors exhibit high levels of nuclear ATF3 expression." (PMID 18808719, 2008). "Human breast tumor samples, as well as normal breast tissue, were similarly analyzed for ATF3 expression." (PMID 18808719, 2008). "Direct measurements of ATF3 copy number by quantitative PCR indicated some amplification in ~80% of human breast tumors." (PMID 18808719, 2008). "As part of a more extensive study of gene expression signatures in human breast tumors, expression of ATF3 was measured in a series of 28 early (stage 1–2) breast tumor samples." (PMID 18808719, 2008). "Recently, Hai and co-workers also suggested that ATF3 is an oncogene, based primarily on widespread overexpression of ATF3 protein in human breast tumors, detected by immunoblotting." (PMID 18808719, 2008). "ATF3 gene copy number was at least doubled in 80% of the breast tumors examined; protein levels also were elevated in close to 50% of these tumors." (PMID 19116033, 2008). "Additionally, immunohistochemical analyses of human breast tumors revealed that ATF3 expression in most tumors is stromal but that 20–25% of human tumors exhibit strong nuclear ATF3 expression in the epithelial compartment of the tumor." (PMID 33652981, 2021). "Atf3 gene expression was shown to be increased in human breast tumors." (PMID 30373101, 2018). "The finding of high levels of nuclear expression of ATF3 in a subset of human breast tumors raises the possibility that this transgenic model may provide clues as to the genesis of at least some human cancers." (PMID 18808719, 2008). "Furthermore, overexpression of ATF3 protein in 50% of human breast tumors has recently been reported by Hai and co-workers." (PMID 18808719, 2008). "A subset of human breast tumors expresses high levels of ATF3, suggesting that ATF3 may play an oncogenic role in human breast tumorigenesis." (PMID 18808719, 2008). "A subset of human breast tumors expresses high levels of ATF3, suggesting that ATF3 may play an oncogenic role in human breast tumorigenesis, and therefore may be useful as either a biomarker or therapeutic target." (PMID 18808719, 2008). "A better understanding of the molecular mechanisms by which ATF3 overexpression initiates mammary tumorigenesis in the transgenic mouse model may provide new biomarkers and/or therapeutic targets for a subset of human breast tumors." (PMID 18808719, 2008). "ATF3 increased apoptosis in untransformed MCF10A mammary epithelial cells, while it inhibited apoptosis in MCF10A breast tumor cells." (PMID 22768301, 2012). "As an example, analysis of publicly available datasets from human breast tumors showed that Atf3 expression was higher in the breast tumor stroma from patients with chemotherapy than those without." (PMID 30373101, 2018).
colitis (9 papers, 2018 to 2025). Inflammation of the colon. "Elevating HDL-C by CETPi before or even after the onset of experimental colitis reduced disease severity, which is associated with an ATF3-dependent anti-inflammatory reprogramming of macrophages and with enhanced gut barrier function." (PMID 40484317, 2025). "DSS-induced colitis was selected because it is well documented that DSS administration in mice causes epithelial barrier dysfunction which we believe ATF3 has a major regulatory role." (PMID 30455690, 2018). "Loss of ATF3 enhances intestinal permeability and susceptibility to colitis." (PMID 32859970, 2020). "Deficiency of ATF3 in CD4+ T cells aggravates colitis in mice, which could be alleviated by the transfer of follicular helper T (TFH) or IgA+ B cells." (PMID 32922364, 2020). "Intriguingly, loss of ATF3 disrupts this niche leading to decreased Ki67+ proliferating transit-amplifying (TA) cells and total crypt numbers (i.e., regeneration capability) at the steady state or during colitis." (PMID 30455690, 2018). "Together, these data suggest that evacetrapib protects mice from colitis via upregulating ATF3-promoted anti-inflammatory transcriptional reprogramming of macrophages as well as enhanced gut barrier function." (PMID 40484317, 2025). "Atf3 has been shown to protect against colitis by regulating T follicular helper (Tfh) cells in the gut, leading to greatly diminished germinal center cells in Peyer’s patches." (PMID 37954612, 2023). "In experimental colitis, ATF3 modulated the gut epithelial barrier functions and protected against inflammation-associated injuries in mice." (PMID 34944038, 2021). "Together, these results indicate that restoring epithelial ATF3 signaling through wild-type organoid transplantation can effectively attenuate inflammatory conditions after DSS-induced colitis." (PMID 30455690, 2018). "To further strengthen our conclusion that epithelial ATF3 mediates protection during DSS colitis, we obtained ATF3 flox mice and generated epithelium-specific ATF3 conditional (Vil-Cre+ATF3F/F) knockout mice." (PMID 30455690, 2018). "Taken together, we concluded ATF3−/− mice suffer lethal colitis due to impaired epithelial regeneration and immunity, as well as enhanced cellular stress." (PMID 30455690, 2018). "Given the limited understanding of effective treatments for these conditions, NETosis and ATF3 could also be viable targets for managing the initial progression of colitis and IBD-like disease." (PMID 38791301, 2024). "ATF3 also ameliorates colitis and facilitates intestinal regeneration." (PMID 34944038, 2021). "Above these results, we predict that CH25H might protect intestine from DSS-induced colitis by promoting ATF3 expression." (PMID 32859970, 2020). "We found ATF3 is central to intestinal homeostasis and provides protection during colitis." (PMID 30455690, 2018). "We found epithelium-specific ATF3 conditional knockout mice also recapitulate most phenotypes of DSS colitis observed in global ATF3−/− mice, including increased disease activity index, more shortened colon length, reduced total crypt numbers and impaired epithelial regeneration." (PMID 30455690, 2018). "Loss of ATF3 led to decreased crypt numbers, more shortened colon length, impaired ileal fucosylation at the steady state, and lethal disease activity during DSS-induced colitis which can be effectively ameliorated by rectal transplantation of wild-type colonic organoids." (PMID 30455690, 2018). "Thus, ATF3 seems to play a more dominant role in the downstream of IL-22 signaling circuit in vivo, compared to a role in IL-6 signaling, as global ATF3−/− mice were more susceptible to DSS colitis and Citrobacter infection." (PMID 30455690, 2018). "Taken together, our findings reveal a protective role for 25-HC in DSS-induced colitis and the ability of CH25H to maintain epithelial gut barrier function through ATF3 expression." (PMID 32859970, 2020).
colitis (continued). "Together, these results exclude the potential contribution of non-epithelial ATF3 from other cell types to colitis pathogenesis in our experimental model." (PMID 30455690, 2018). "However, in ATF3−/− mice, we did not observe any enlarged lymph nodes, splenomegaly or cellularity defects associated with other lymphoid organs at the steady state or during DSS colitis (data not shown)." (PMID 30455690, 2018). "While naïve ATF3−/− mice showed no signs of disease activity, notably, DSS-treated ATF3−/− mice developed more severe colitis with lethal disease activity leading to reduced survival rate and much shortened colon length compared to wild-type mice." (PMID 30455690, 2018).
esophageal squamous cell carcinoma (9 papers, 2014 to 2021). Esophageal squamous cell carcinoma (ESCC) is a type of esophageal carcinoma (EC) that can affect any part of the esophagus, but is usually located in the upper or middle third. "Currently, several studies have shown that ATF3 plays tumor suppressing roles in different cancer types, including colon cancer and esophageal squamous cell carcinomas (ESCC)." (PMID 26917416, 2016). "ATF4 hasbeen reported to promote esophageal squamous cell carcinoma invasion and metastasis, whereas the effect of ATF3 on metastasis in different types of cancer remains controversial." (PMID 26913720, 2016). "Here, we sought to explore the expression and biological function of ATF3 in esophageal squamous cell carcinomas (ESCC)." (PMID 25149542, 2014). "Similarly, ATF3 is down-regulated in esophageal squamous cell carcinoma." (PMID 33407456, 2021). "For instance, ATF3 was found to be down-regulated in esophageal squamous cell carcinoma (ESCC) lesions, and forced expression of ATF3 led to decreased growth and invasive properties of ESCC cells in vitro and in vivo through regulation of MDM2 expression." (PMID 32373541, 2020).
ischemic stroke (9 papers, 2019 to 2025). A stroke disorder caused by obstruction of blood flow to the brain, due to thrombotic (local blood clot formation) or embolic (due to a blood clot or other material traveling from another site) event. "Consequently, delineating the ability for ATF3 to trans-repress CTMP will help to broaden insights into the development of more effective therapies to restrain brain damage caused by ischemic stroke." (PMID 36768628, 2023). "Silencing ATF3 significantly decreased the expression of AQP4 and reduced water content in the brain of ischemic stroke rats compared with lv-NC group (p < 0.01), whereas the inhibitory of silencing ATF3 was weakened by anisomycin (p < 0.01)." (PMID 40621504, 2025). "The MAPK pathway agonist anisomycin was further administrated in ischemic stroke rats, in order to investigate the role of ATF3 in ischemic stroke and mitochondrial homeostasis through the MAPK pathway." (PMID 40621504, 2025). "This study suggested ATF3 as a promising marker for ischemic stroke and revealed the MAPK signaling pathway as the potential regulatory pathway of ATF3 in ischemic stroke." (PMID 40621504, 2025). "A study revealed that in patients with silent cerebral infarction or ischemic stroke, the serum ATF3 level elevated within 24 h." (PMID 41181154, 2025). "Collectively, silencing ATF3 attenuated the progression of ischemic stroke and improved mitochondrial homeostasis through regulating the MAPK pathway." (PMID 40621504, 2025). "In this study, the levels of ATP and NAD + were both downregulated after induction of ischemic stroke, while silencing ATF3 significantly upregulated the expression of ATP and NAD+." (PMID 40621504, 2025). "In this study, bioinformatics analysis was used to screen differential expressed genes (DEGs) between ischemic stroke rats and ischemic stroke rats with silencing ATF3, and to reveal the enriched signaling pathways for DEGs." (PMID 40621504, 2025). "In conclusion, the results demonstrated that silencing ATF3 improved mitochondrial homeostasis and inhibited ischemic stroke progression through inactivating the MAPK signaling pathway." (PMID 40621504, 2025). "The mitogen activated protein kinase (MAPK) agonist, anisomycin, was used to investigate the regulation of ATF3 in ischemic stroke and mitochondrial homeostasis via the MAPK pathway." (PMID 40621504, 2025). "This study aimed to investigate the role of activating transcription factor 3 (ATF3) in ischemic stroke and mitochondrial homeostasis." (PMID 40621504, 2025). "In a previous study, ATF3-knockout mice, compared to wild-type mice, exhibited worse neurological outcomes and large damaged regions after SCI or ischemic stroke, indicating that ATF3 has a neuroprotective function." (PMID 41181154, 2025). "Anisomycin notably reversed the effect of silencing ATF3 on ischemic stroke and mitochondrial homeostasis." (PMID 40621504, 2025). "Further studies are needed to investigate the mechanism underlying ATF3's neuroprotective role in SCI and ischaemic stroke." (PMID 38649772, 2024). "Mechanistically, we reveal that ATF3 exhibits a neuroprotective function after SCI or ischaemic stroke in mouse models." (PMID 38649772, 2024). "Specifically, we demonstrate that ATF3 is induced exclusively in mouse spinal cord or cortex neurons shortly after SCI or ischaemic stroke, respectively, and its levels in the blood are elevated in mice after SCI or ischaemic stroke." (PMID 38649772, 2024). "Consistent with previous report, we also confirmed that Atf3 KO mice experienced more extensive neurological damage following ischaemic stroke when compared to WT mice." (PMID 38649772, 2024). "Since ATF3 was induced exclusively in neurons 1 day after SCI or ischaemic stroke, we explored the possibility of detecting ATF3 protein levels in the peripheral blood as a potential biomarker." (PMID 38649772, 2024).